C5orf15 (chromosome 5 open reading frame 15)
Synonyms: KCT2; HTGN29
Tractability: Antibody: UniProt predicts a signal peptide or a membrane-spanning region. PROTAC: ubiquitination databases record sites on it; its protein half-life has been measured.
Gene: Protein-coding gene on chromosome 5 (133,955,510 to 133,968,674, reverse strand). Ensembl gene ENSG00000113583.
Subcellular location: Membrane
Subcellular location (Human Protein Atlas): Golgi apparatus
Gene Ontology:
Cellular component: membrane
Genetic constraint (gnomAD): Loss-of-function variants: 10 observed, 17.4 expected, observed/expected ratio (o/e) 0.57, 90% interval 0.35 to 0.98. The upper end of that interval is the gene's LOEUF score, 0.98, which puts it in group 4 of 6, group 1 being the genes least tolerant of losing a copy. Missense variants: 298 observed, 317.43 expected, observed/expected ratio (o/e) 0.94, 90% interval 0.85 to 1.03. Synonymous variants: 118 observed, 128.63 expected, observed/expected ratio (o/e) 0.92, 90% interval 0.79 to 1.07.
Homologues: Orthologues: chimpanzee C5H5orf15 (99% identical), macaque C6H5orf15 (96% identical), dog C5orf15 (79% identical), pig C5orf15 (76% identical), rabbit C5orf15 (71% identical), guinea pig C5orf15 (68% identical), rat C10h5orf15 (65% identical), mouse 9530068E07Rik (62% identical), zebrafish si:ch73-269m14.2 (37% identical), Caenorhabditis elegans tgn-38 (21% identical).
Diseases named in the same sentence as C5orf15 in open-access papers:
C5orf15 is named in the same sentence as 8 diseases in open-access papers, as found by Europe PMC text mining. Sharing a sentence is not in itself a finding about the gene and the disease. The quoted sentences say what the papers report.
glioblastoma (1 paper, 2022). The most malignant astrocytic tumor (WHO grade IV). "For the remaining seven DEPCGs (ZWILCH, RPGR, ZNF460, ZNF528, QTRT2, C5orf15 and CNTRL), no previous functional associations were found with glioblastoma progression, despite a number of them being associated with other cancer types." (PMID 36497269, 2022).
tumor (1 paper, 2023). "Results showed that the expression level of genes including MORF4L2, CTSL1, WIPF1, CXCL13, C5orf15, LIPA, and ISG20 significantly elevated in tumor tissues." (PMID 36639648, 2023).
C5orf15 also shares sentences with these, for which no sentence is quoted: amyotrophic lateral sclerosis (1 paper); arrhythmogenic right ventricular dysplasia 5 (1); cancer (1); Charcot-Marie-Tooth disease (1); conduct disorder (1); neuropathy (1).